MCL1 (MCL1 apoptosis regulator, BCL2 family member)
Diseases named in the same sentence as MCL1 in open-access papers (continued):
Sharing a sentence is not in itself a finding about the gene and the disease.
T-cell leukemia (3 papers, 2011 to 2018). A malignant disease of the T-lymphocytes in the bone marrow, thymus, and/or blood. "It has been reported that down-regulation of MCL1 sensitizes T-cell leukemia cells to treatment with glucocorticoids." (PMID 22185641, 2011). "To determine whether BCL family can also facilitate gene editing in other cell lines, we tested the effects of BCL-XL, BCL2, and MCL1 in mouse ESCs, HEK293T (human embryonic kidney cells), K562 (human erythroleukemia cells), and Jurkat (T-cell leukemia) cells." (PMID 30239926, 2018).
thymoma (3 papers, 2013 to 2023). A neoplasm arising from the epithelial cells of the thymus. "Furthermore, copy number gains of MCL1, another member of the BCL2 family gene, have been observed in 51% of TETs, predominantly in aggressive histological subtypes (83% in type B2/B3 thymomas, 70% in type B3 thymomas and 57% in thymic carcinomas)." (PMID 37849766, 2023).
type 1 diabetes (3 papers, 2019 to 2020). "Consistent with this, we have shown previously that MCL-1 levels are reduced in certain beta cells in the islets of people with type 1 diabetes and it is worth noting that MCL-1 was also downregulated following the treatment of INS-1E cells with proinflammatory cytokines." (PMID 30338340, 2019).
adenocarcinoma of the uterine cervix (2 papers, 2020 to 2023). "MCL1 also displayed CNVs in non-small lung cancer and uterine cervix adenocarcinoma and impact on survival of patients." (PMID 36937870, 2023). "For patients with adenocarcinoma of the uterine cervix receiving definitive CRT, prognostic information can be supplemented by MCL1 amplification, the TMN, and the TNF-α H score." (PMID 32527042, 2020).
anaplastic thyroid cancer (2 papers, 2016 to 2019). "Both OB3 and leptin reduced PCNA expression significantly and increased the expression of c-Myc and MCL-1 slightly in anaplastic thyroid cancer cells." (PMID 27050378, 2016). "For example, the poor prognostic marker and anti-apoptotic protein, MCL1 (Myeloid Cell Leukemia Sequence 1 [BCL2-related]), is a target of quinacrine, as shown in anaplastic thyroid cancer." (PMID 31497252, 2019).
anemia (2 papers, 2013 to 2024). A reduction in the number of red blood cells, the amount of hemoglobin, and/or the volume of packed red blood cells. "In summary, Noxa and its antagonist Mcl-1 are part of an important component of the mechanisms to re-establish RBC numbers upon blood loss and modulation of this pathway could be envisaged in therapeutic options for treatment of anemia." (PMID 23975731, 2013).
atherosclerosis (2 papers, 2015 to 2019). A disease characterized by the build-up of fatty material and calcium deposition in the arterial wall resulting in partial or complete occlusion of the arterial lumen. "To assess the relevance of Mcl-1-dependent MGC formation in human atherosclerosis, we quantified MGCs in human plaques." (PMID 31601924, 2019). "MiR-29b suppressed the proliferation and migration of SMCs and prevents atherosclerosis through the inhibition of their targets Mcl-1 and MMP2." (PMID 25664324, 2015). "We next investigated the role of Mcl-1 in macrophages and foam cells in atherosclerosis, reasoning that hyperlipidemia could unleash a role for Mcl-1 in plaque macrophage biology, as has been described for macrophages undergoing infection." (PMID 31601924, 2019). "Here, we investigated the impact of myeloid Mcl-1 deletion in atherosclerosis." (PMID 31601924, 2019).
bladder (2 papers, 2015 to 2022). "Anti-apoptotic Mcl-1 downregulated by miRNA-3614-5p suggests that loss of miRNA-3614-5p may contribute to prostate tumorigenesis." (PMID 35457012, 2022). "Consistent with the repression of STAT3 pathway, which are highly relevant to bladder carcinogenesis, the suppression of STAT3 was further confirmed by the reduction of its downstream targets, such as Bcl-2, Bcl-xL and Mcl-1, at both mRNA and protein levels." (PMID 25849286, 2015).
bone marrow failure (2 papers, 2018 to 2021). "Until recently a truly selective and potent small molecule inhibitor of MCL‐1 had yet to be developed, and a worrying caveat is that genetic deletion of MCL‐1 in mouse models resulted in bone marrow failure and myocardial toxicity." (PMID 35846088, 2021). "A worrying caveat to targeting MCL‐1 is that deletion of MCL‐1 in mouse models resulted in bone marrow failure and myocardial toxicity." (PMID 35846088, 2021). "Until now a truly selective and potent small molecule inhibitor of MCL-1 has not been developed and a worrying caveat is that genetic deletion of MCL-1 in mouse models resulted in bone marrow failure and myocardial toxicity." (PMID 30701031, 2018). "In addition, deletion of MCL-1 in mouse models resulted in bone marrow failure and myocardial toxicity." (PMID 30701031, 2018).
breast adenocarcinoma (2 papers, 2021). "MCL1 is a crucial regulator of apoptosis that is triggered by anti-tubulin chemotherapeutics in various malignancies, such as ovarian and breast adenocarcinomas." (PMID 34638252, 2021).
B‐cell lymphoblastic leukemia (2 papers, 2022 to 2026). "It has been previously reported that FAO genes are downregulated following the genetic deletion of Mcl‐1 in mouse B‐cell lymphoblastic leukemia cells and liver tissue." (PMID 41420072, 2026).
cardiac hypertrophy (2 papers, 2016 to 2020). "Among them, those coding for DUSP family members, CDKN1A, BTG2, GADD45B,34, and MCL-1 have been previously shown to be upregulated in human myocardial tissues in response to stress and/or DNA damage and to play a role in the regulation of cardiac hypertrophy and remodeling in animal models." (PMID 31924244, 2020).
chordoma (2 papers, 2020). Chordomas are rare malignant tumors arising from embryonic remnants of the notochord in axial skeleton. "Consistent with our work, we observed CDK9 inhibition to induce a concomitant decrease of Mcl-1 and associated antiapoptotic factors, with an overall suppression of chordoma cell growth." (PMID 31892980, 2020). "CDK9 silencing with siRNA decreased growth and proliferation of chordoma cells and lowered levels of Mcl-1 and RNA polymerase II (RNAP II) phosphorylation." (PMID 31892980, 2020). "While the precise molecular effects of TOPK inhibition on chordoma are undefined, we show a significant reduction of the anti‐apoptotic proteins Mcl‐1 and Survivin and increased apoptotic cleavage of PARP." (PMID 32960500, 2020). "Downregulation of Mcl-1 was also observed in the CDK9 siRNA transfected chordoma cells." (PMID 31892980, 2020). "We found inhibition of CDK9 in chordoma cell lines to decrease p-RNAP II Ser-2 and Mcl-1 while also suppressing proliferation and inducing apoptosis." (PMID 31892980, 2020). "Collectively, the decrease in Mcl-1 and Survivin reasonably explains how inhibition of CDK9 may induce apoptosis in chordoma cell lines." (PMID 31892980, 2020).
choroidal melanoma (2 papers, 2017 to 2021). Malignant tumor of melanocytes of the choroid. "In summary, the data demonstrated that the NOXA/Mcl-1 axis is involved in the anticancer effect of LiCl in choroidal melanoma cells." (PMID 33557839, 2021). "Flow cytometry analysis showed that Mcl-1 overexpression reduced LiCl–induced apoptosis in human choroidal melanoma cells." (PMID 33557839, 2021). "Overall, our findings indicate that the NOXA/Mcl-1 axis contributes to the intrinsic apoptosis induced by pemetrexed plus cisplatin in choroidal melanoma cells." (PMID 28863158, 2017). "To summarize, the c-FLIP and NOXA/Mcl-1 axis participated in the synergistic effect of pemetrexed plus cisplatin in human choroidal melanoma cells." (PMID 28863158, 2017). "Therefore, we conclude that NOXA and Mcl-1 contribute to the synergistic effect of the co-treatment in choroidal melanoma cells." (PMID 28863158, 2017).
chronic myeloproliferative neoplasms (2 papers, 2011 to 2016). "Thus, further preclinical evaluation of combinations of JAK2 inhibitors with Bcl-2 family antagonists that also tackle Mcl-1, besides Bcl-xL, is warranted to assess the therapeutic potential for the treatment of chronic myeloproliferative neoplasms." (PMID 21247487, 2011).
co-infection (2 papers, 2023). "This assay is based on the co-infection of isolated CD4+ T-cells from HIV-seronegative donors with an HIV reporter construct and a virus expressing two antiapoptotic proteins (MCL1 and Bcl2)." (PMID 37874295, 2023).
Cognitive impairment (2 papers, 2022 to 2025). Abnormal cognition is characterized by deficits in thinking, reasoning, or remembering. "This study aims to determine whether higher or lower expression of Cdk5 levels in the blood of AD and Mild Cognitive Impairment (MCI) patients is associated with an increased risk of cognitive decline by correlating with Mcl1 level." (PMID 41154594, 2025). "This study evaluated the expression levels of Cdk5 and Mcl1 (Cdk5’s substrate) in blood samples of 61 AD, 55 Mild Cognitive Impairment (MCI), and 57 Geriatric Controls (GC), and explored the in vitro inhibition of Cdk5." (PMID 41154594, 2025).
colon adenoma (2 papers, 2014 to 2022). An adenoma that arises from the colon. "Mcl-1 a member of Bcl2 family and an inhibitor of apoptosis, showed a significantly higher expression in colon adenoma and carcinoma patient compared to healthy colonic epithelium." (PMID 24495750, 2014).
Crohn disease (2 papers, 2017 to 2020). A gastrointestinal disorder characterized by chronic inflammation involving all layers of the intestinal wall, noncaseating granulomas affecting the intestinal wall and regional lymph nodes, and transmural fibrosis. "We employed Mycobacterium avium paratuberculosis (MAP) infection in Crohn’s disease (CD) as a model to demonstrate the role of Notch-1/IL-6 signaling on MCL-1 based apoptosis and intracellular MAP infection and persistence." (PMID 33072191, 2020).
epilepsy (2 papers, 2025). A brain disorder characterized by episodes of abnormally increased neuronal discharge resulting in transient episodes of sensory or motor neurological dysfunction, or psychic dysfunction. "Our findings demonstrate that LITAF regulates MCL‐1 ubiquitination, significantly impacting mitochondrial autophagy and contributing to neuronal damage in epilepsy." (PMID 39764629, 2025). "The study reveals that the E3 ubiquitin ligase LITAF promotes MCL‐1 ubiquitination, impairing mitophagy and exacerbating oxidative stress‐induced neuronal damage in epilepsy." (PMID 39764629, 2025). "This study aims to investigate how the E3 ubiquitin ligase LITAF influences mitochondrial autophagy by modulating MCL‐1 ubiquitination, and its role in the development of epilepsy." (PMID 39764629, 2025). "Targeting LITAF and its regulation of MCL‐1 may offer a novel therapeutic strategy for mitigating neuronal damage and treating epilepsy." (PMID 39764629, 2025).
fatty liver (2 papers, 2019 to 2020). "We observed that excessive hepatocyte apoptosis due to Mcl1 loss drives HCC development in fatty liver disease." (PMID 32015322, 2020). "We propose that proapoptotic microenvironment in NASH promotes hepatocarcinogenesis and that the anti-apoptotic protein Mcl1 serves as a tumor suppressor in fatty liver." (PMID 32015322, 2020). "Thus, this study provides evidence that excessive hepatocyte apoptosis is tumor promoting also in fatty liver disease and the anti-apoptotic protein Mcl1 is tumor suppressive in mouse liver affected by NASH." (PMID 32015322, 2020).
fibrosis (2 papers, 2017 to 2025). the formation of excess fibrous connective tissue in an organ or tissue in a reparative or reactive process. "A second cytokine, IL-8, can also increase the expression of MCL-1 and elevated serum levels of IL-8 are associated with fibrosis in chronic liver disease." (PMID 28190086, 2017). "Future studies should validate the efficacy of MCL-1-targeted strategies in other models of renal injury and further dissect the diverse roles of senescence across kidney cell populations in fibrosis and CKD progression." (PMID 41298369, 2025).
gastrointestinal stromal tumor (2 papers, 2014 to 2015). "Several patients had multiple aberrations; a patient with wild-type gastrointestinal stromal tumor harbored five alterations (MDM4, MCL1, KIT, AKT3, and PDGRFA)." (PMID 26328274, 2015).
hepatitis C (2 papers, 2024 to 2025). "GSEA further revealed that MCL1 is significantly enriched in multiple virus-related pathways, including hepatitis C, influenza A, measles, the RIG-I-like receptor signaling pathway, and the HIV-1 viral life cycle." (PMID 40872527, 2025).
hyperlipidemia (2 papers, 2019 to 2025). "Our results clearly identify Mcl-1 as a macrophage survival protein under hyperlipidemia and uncover a hitherto unknown role for Mcl-1 in MGC formation." (PMID 31601924, 2019). "Thus, under conditions of hyperlipidemia Mcl-1 appears to be an active regulator of macrophage survival as well as of macrophage lipid loading." (PMID 31601924, 2019). "Thus, our results unveil a hitherto unknown link between Mcl-1 and MGC formation, which is influenced by hyperlipidemia, an association potentially preserved in human atherosclerotic lesions as well." (PMID 31601924, 2019). "Stratification by disease status and hyperlipidemia revealed that MCL1, F13A1, TLR8, and TAGAP were significantly upregulated in patients with both AS and hyperlipidemia compared with healthy individuals without hyperlipidemia (p < 0.05)." (PMID 41583468, 2025).
Hypertension (2 papers, 2016 to 2024). The presence of chronic increased pressure in the systemic arterial system. "We found that miR-20a-5p regulates the expression of MCL1, and both genes are differentially expressed by race in hypertension." (PMID 27779208, 2016). "We identified novel mRNA-microRNA pairs potentially involved in hypertension-related pathways and differently-expressed, including MCL1/miR-20a-5p, APOL3/miR-4763-5p, PLD1/miR-4717-3p, and PLD1/miR-4709-3p." (PMID 27779208, 2016).
invasive breast carcinoma (2 papers, 2016 to 2017). A carcinoma that infiltrates the breast parenchyma. "MCL-1 was present in the nucleus and cytoplasm of invasive breast cancers and is expressed by luminal, basal and HER2 positive subtypes." (PMID 29146920, 2017). "We then explored the prognostic significance of MCL-1 using tissue microarrays from a cohort of 246 patients diagnosed with invasive breast carcinoma." (PMID 27931239, 2016).
invasive ductal carcinoma (2 papers, 2016 to 2024). "Increased MCL-1 copy number was also more frequently observed in invasive ductal carcinoma compared with normal tissues (TCGA, Oncomine)." (PMID 27931239, 2016). "Considering the gradual progression of benign to malignant tumors in dogs and the higher MCL-1 expression in invasive ductal carcinoma than in normal human tissues, the observed pattern of increased malignancy correlating with higher MCL-1 expression was not unexpected." (PMID 39012900, 2024).
Lymphadenopathy (2 papers, 2008 to 2021). Enlargement (swelling) of a lymph node. "Nonetheless, the overexpression of Mcl-1 exacerbated lpr autoimmune phenotypes and accelerated the morbidity with excessive weight loss, breathing difficulties and severe lymphadenopathy in the Faslpr/lpr mouse model (non-functional Fas death receptor)." (PMID 34336857, 2021). "Both splenomegaly and lymphadenopathy were observed in this Mcl-1 transgenic model." (PMID 34336857, 2021). "Bcl-2-deficient mice and mice lacking myeloid cell leukemia 1 (Mcl-1) in the hematopoietic system exhibit profound lymphopenia, whereas mice overexpressing a Bcl-2 transgene throughout the hematopoietic compartment show marked lymphadenopathy." (PMID 18275830, 2008).
lymphoid tumor (2 papers, 2023 to 2024). "AZD4573, a clinical congener of AZ5576, was shown to suppress transcription of the pro-survival proteins Mcl-1 and Bfl-1/A1 in lymphoid tumors, and exhibited anti-tumor effects in AML models in vivo via an Mcl-1 dependent mechanism." (PMID 36998071, 2023). "Given the heterogeneity of lymphoid tumors, this supports a model where multiple factors will be important for sensitivity to CDK9i, not limited to Mcl-1, and will also account for ultimate drug resistance." (PMID 36998071, 2023).
meningioma (2 papers, 2022 to 2024). A generally slow growing tumor attached to the dura mater. "Similarly, the expression of CA-IX and Bcl-2 members family (regulators of apoptosis in tumor cells) including RTRAIL-R2, RTRAIL-R4, caspase-8, cFLIP, Bak, Bcl-XL, and Mcl-1 did not associate with OS or PFS of meningioma patients (p>0.05)." (PMID 38758750, 2024). "Although the dependency on BCL-xL is often caused by alterations in the expression of other BCL-2 family proteins, such as MCL-1 and NOXA, the combination of everolimus and gemcitabine in malignant meningioma cells did not consistently alter the expression of these proteins in the present study." (PMID 35406478, 2022).
metastasis (2 papers, 2020). The spread or migration of cancer cells from one part of the body (where they first appeared) to another. "Aberrant Mcl-1 expression is frequently found in CRCs and significantly correlated with advanced tumor stages, lymph node metastasis, resistance to chemotherapy, and poor patient survival 32-35." (PMID 32724460, 2020).
metastatic cancer (2 papers, 2011 to 2012). A carcinoma which has spread from the original site of growth to another anatomic site. "Since the metastatic PC3-MM2 cells showed the down-regulation of c-FLIP and Mcl-1, we determined the level of c-Myc expression in metastatic cancer cells." (PMID 21513580, 2011). "Since c-FLIPL and Mcl-1 were known as substrates of caspases, it could be possible that TRAIL-induced potent activation of caspases in metastatic cancer cells led to accelerated down-regulation of c-FLIPL and Mcl-1." (PMID 21513580, 2011). "Therefore, our results suggest that increased sensitivity to TRAIL in metastatic cancer cells may be in part due to increased expression of c-Myc in the cells, which is associated with up-regulation of DR5 cell surface expression and down-regulation of c-FLIP and Mcl-1." (PMID 21513580, 2011).
myeloid malignancies (2 papers, 2024 to 2025). "However, in response to BCL-2 inhibition with venetoclax, myeloid malignancies tend to upregulate and depend on other members of BCL-2 family, such as myeloid cell leukemia-1 (MCL-1), as mechanisms of venetoclax resistance." (PMID 40756330, 2024).
nevus (2 papers, 2018 to 2022). Nevus (or naevus, plural nevi or naevi, from nævus, Latin for "birthmark") is the medical term for sharply circumscribed[1] and chronic lesions of the skin or mucosa. "Because nevi are populated by senescent-like melanocytes, we reasoned that the combination of ABT-263 and MCL-1 inhibition could potentially lead to nevus reduction by inducing targeted cell death." (PMID 36564381, 2022).
obstructive sleep apnea (2 papers, 2012 to 2021). "Previous studies have shown that the Bax/Mcl-1 balance can affect hPMN survival during intermittent hypoxia and obstructive sleep apnea." (PMID 34484191, 2021).
osteoarthritis (2 papers, 2021 to 2025). A noninflammatory degenerative joint disease occurring chiefly in older persons, characterized by degeneration of the articular cartilage, hypertrophy of bone at the margins and changes in the synovial membrane. "Although the specific role of MCL1 in osteoarthritis is merely known, a study has discovered that MCL1 could serve as a target of miR203 to inhibit cartilage degeneration." (PMID 34670585, 2021). "LASSO regression and the Boruta algorithm validated the significant predictive ability of genes such as MCL1, JUN, and GADD45B, with their high AUC values indicating potential as osteoarthritis biomarkers." (PMID 40826778, 2025). "The results indicated that MCL1, JUN, and GADD45B exhibited relatively high AUC values, highlighting their significant classification ability and potential as biomarkers for osteoarthritis." (PMID 40826778, 2025).